MICAL3 (microtubule associated monooxygenase, calponin and LIM domain containing 3)
Description:
Monooxygenase that promotes depolymerization of F-actin by mediating oxidation of specific methionine residues on actin to form methionine-sulfoxide, resulting in actin filament disassembly and preventing repolymerization. In the absence of actin, it also functions as a NADPH oxidase producing H(2)O(2). Seems to act as Rab effector protein and plays a role in vesicle trafficking. Involved in exocytic vesicles tethering and fusion: the monooxygenase activity is required for this process and implicates RAB8A associated with exocytotic vesicles. Required for cytokinesis. Contributes to stabilization and/or maturation of the intercellular bridge independently of its monooxygenase activity. Promotes recruitment of Rab8 and ERC1 to the intercellular bridge, and together these proteins are proposed to function in timely abscission.
Synonyms: MICAL-3; KIAA0819
Tractability: Small molecule: a structure with a bound ligand is known. Antibody: its Gene Ontology location is reachable by antibodies, with high confidence. PROTAC: ubiquitination databases record sites on it; its protein half-life has been measured.
Gene: Protein-coding gene on chromosome 22 (17,787,649 to 18,024,561, reverse strand). Ensembl gene ENSG00000243156.
Subcellular location: Cytoplasm; Cytoplasm, cell cortex; Cytoplasm, cytoskeleton; Nucleus; Midbody; Cytoplasm, cytoskeleton, spindle; Cytoplasm, cytoskeleton, cilium basal body
Subcellular location (Human Protein Atlas): Midbody ring; Nucleoplasm; Cytosol; Plasma membrane
Gene Ontology:
Molecular function: actin binding; molecular adaptor activity; FAD binding; oxidoreductase activity, acting on paired donors, with incorporation or reduction of molecular oxygen, NAD(P)H as one donor, and incorporation of one atom of oxygen; F-actin monooxygenase activity
Biological process: actin filament depolymerization; cytoskeleton organization; actin cytoskeleton organization
Cellular component: cytoplasm; cytosol; Flemming body; midbody; nucleoplasm; nucleus; cell cortex; cytoskeleton; spindle
Genetic constraint (gnomAD): Loss-of-function variants: 54 observed, 169.87 expected, observed/expected ratio (o/e) 0.32, 90% interval 0.25 to 0.4. The upper end of that interval is the gene's LOEUF score, 0.4, which puts it in group 1 of 6, group 1 being the genes least tolerant of losing a copy. Missense variants: 2,298 observed, 2,466.3 expected, observed/expected ratio (o/e) 0.93, 90% interval 0.9 to 0.96. Synonymous variants: 1,052 observed, 1,007.4 expected, observed/expected ratio (o/e) 1.04, 90% interval 0.99 to 1.1.
Homologues: Orthologues: chimpanzee MICAL3 (99% identical), macaque MICAL3 (98% identical), rabbit MICAL3 (90% identical), dog MICAL3 (88% identical), rat Mical3 (87% identical), mouse Mical3 (87% identical), pig MICAL3 (82% identical), tropical clawed frog mical3 (68% identical), zebrafish mical3a (65% identical). Paralogues in human: MICAL2 (29% identical), MICAL1 (24% identical), DST (12% identical), MACF1 (12% identical), SYNE1 (11% identical), PLEC (11% identical), SPTB (11% identical), SPTBN1 (10% identical), SPTBN4 (10% identical), SPTBN2 (10% identical), SPTBN5 (10% identical), SYNE2 (10% identical), and 24 more.
Diseases named in the same sentence as MICAL3 in open-access papers:
MICAL3 is named in the same sentence as 16 diseases in open-access papers, as found by Europe PMC text mining. Sharing a sentence is not in itself a finding about the gene and the disease. The quoted sentences say what the papers report.
angina (1 paper, 2025). "Similarly, the methylation levels at cg14480594 in the ACTL7A gene, cg17387122 in the MICAL3 gene, and cg02787562 in the SUN1 gene, which are associated with PM10, were significantly positively correlated with the risk of MI, angina, and HF, respectively (FDR < 0.05)." (PMID 41420191, 2025).
breast carcinoma (1 paper, 2024). "Approaches that therapeutically target this niche have gained attention, such as treatment strategies targeting Wnt signaling in colorectal and pancreatic cancers and semaphorin signaling via MICAL3 in breast cancer." (PMID 39420119, 2024).
Hepatic steatosis (1 paper, 2013). Steatosis is a term used to denote lipid accumulation within hepatocytes. "This final list includes six genes associated with ALT elevation and/or hepatic steatosis (MAPK10, CPN1, TRIB1, PNPLA3, SAMM50 and MICAL3)." (PMID 23813869, 2013).
Infertility (1 paper, 2024). "In addition, the application of MICAL3 inhibitor supplies a novel intervention for patients suffering from infertility caused by CHK1 mutation." (PMID 39358552, 2024).
lung carcinoma (1 paper, 2023). "For example, MICAL3 negatively correlates with KRAS dependency in our model and is frequently enriched in non-smoker related lung cancer." (PMID 37141389, 2023).
synucleinopathies (1 paper, 2024). "Beyond known PD genes GBA1 and LRRK2, rare variants AD genes (CD33, CR1 and PSEN2) and Aβ toxicity modifiers involved in RhoA/actin cytoskeleton regulation (ARGHEF1, ARHGEF28, MICAL3, PASK, PKN2, PSEN2) were shared risk factors across synucleinopathies." (PMID 38496508, 2024).
cancer (4 papers, 2016 to 2024). A tumor composed of atypical neoplastic, often pleomorphic cells that invade other tissues. "In addition, overexpression of some genes, including ABCB1, TPD52L1, HNRNPR and MICAL3, is associated with poor prognosis in various cancers." (PMID 39682186, 2024). "Additional results from the METABRIC datasets showed that ORN could characterize critical mechanisms of cancer and connect them to less studied somatic mutations (e.g., BAP1, MIR604, MICAL3, and telomere activities), which may generate novel hypothesis for targeted therapy." (PMID 33819263, 2021). "Endothelial cells (ECs) of neo-angiogenic capillaries that extensively branch into the cancer mass showed a very intense MICAL2 immunostaining, but no expression of MICAL1 and MICAL3, suggesting a different role of MICAL proteins within neo-angiogenic ECs." (PMID 26689989, 2016).
MICAL3 also shares sentences with these, for which no sentence is quoted: tumor (2 papers); allergic disease (1); autism (1); cat-eye syndrome (1); depression (1); osteoarthritis (1); pancreatic cancers (1); schizophrenia (1); vitamin D deficiency (1).